ABCA2 (ATP binding cassette subfamily A member 2)
Diseases named in the same sentence as ABCA2 in open-access papers:
ABCA2 is named in the same sentence as 41 diseases in open-access papers, as found by Europe PMC text mining. Sharing a sentence is not in itself a finding about the gene and the disease. The quoted sentences say what the papers report.
acute lymphoblastic leukemia (6 papers, 2014 to 2022). Leukemia with an acute onset, characterized by the presence of lymphoblasts in the bone marrow and the peripheral blood. "Overexpression of ABCA2 is associated with a variety of human pathologies and confers drug resistance phenotypes in several cancers including acute lymphoblastic leukemia (ALL) and lung cancer." (PMID 32577155, 2020). "ABCA2, which encodes for a membrane-associated protein of the superfamily of ATP-binding cassette transporters, is over-expressed in epithelial ovarian carcinoma and acute lymphoblastic leukemia patients with poor survival." (PMID 34090518, 2021). "The translational expression of ABCA2 was shown to be a prognostic marker for drug resistance in pediatric acute lymphoblastic leukemia." (PMID 33225420, 2021). "Treatment of acute lymphoblastic leukemia cell lines of CCRF-CEM and Jurkat with methotrexate, vinblastine or doxorubicin caused certain increase of ABCA2 expression in Jurkat cell line, and of ABCA3 in CCRE-CEM and Jurkat cell lines." (PMID 25254091, 2014). "Additionally, ABCA2 is overexpressed in pediatric acute lymphoblastic leukemia and may contribute to multidrug resistance." (PMID 36605200, 2022).
Alzheimer disease (4 papers, 2012 to 2020). A progressive, neurodegenerative disease characterized by loss of function and death of nerve cells in several areas of the brain leading to loss of cognitive function such as memory and language. "Different mutations of ABCA2 have been associated with high risk for Alzheimer’s disease, but up to now, the mechanistic role of ABCA2 in Alzheimer’s disease remains unclear." (PMID 32647530, 2020). "On the other hand, some ABC transporter family genes such as ABCA1, ABCA2, ABCA7 and ABCA12 are associated with Alzheimer's disease." (PMID 23281790, 2012). "Interestingly, the overexpression of ABCB1 and ABCA2 is connected with various neurodegenerative pathologies, especially Alzheimer’s disease." (PMID 32466263, 2020). "Mutations in human ABCA2 (not orthologous to lepidopteran ABCA2) are associated with early-onset of Alzheimer’s disease." (PMID 26583651, 2015).
prostate carcinoma (4 papers, 2021 to 2025). A carcinoma that arises from epithelial cells of the prostate gland. "Inhibition of ABCA2 protein expression has been reported to decrease matrix metalloproteinase expression, thereby inhibiting prostate cancer cell invasion and migration in the TME." (PMID 37563740, 2023). "Deep deletions were significantly more prevalent in prostate cancer tissues compared to breast cancer tissues, where they were relatively rare and limited to ABCG2, ABCC4, ABCA2, ABCC2, and ABCC9." (PMID 40641097, 2025). "Deep deletions were significantly more prevalent in prostate cancer than in breast cancer, with frequent occurrences in ABCG2, ABCG1, ABCC4, ABCA2, ABCC2, ABCC7/CFTR, and ABCC9." (PMID 40641097, 2025). "In contrast, prostate cancer tissues exhibited frequent deep deletions in ABCG2, ABCG1, ABCC4, ABCA2, ABCC2, ABCC7/CFTR, and ABCC9." (PMID 40641097, 2025). "Similarly, in prostate cancer, the alteration frequency varied from 1.1% in ABCG2 to 2.7% in ABCA2, with ABCG2 consistently showing the lowest level of genetic alterations in both cancer types." (PMID 40641097, 2025).
schizophrenia (4 papers, 2005 to 2025). A major psychotic disorder characterized by abnormalities in the perception or expression of reality. "About half of them has been previously associated with schizophrenia in humans, such as Olig1, Fgfr1, Gpr17, Gna12, Abca2, Sox1, Dpm2, and, as a locus for de novo mutations, Rab2a." (PMID 39825014, 2025). "Of 8 genes showing more than two supporting evidences for pathogenic prediction, some of genes (e.g. LRP1, MACF1, DICER1 and ABCA2) harbours de novo mutations provided promising evidence as a strong candidate genes for schizophrenia." (PMID 26666178, 2015). "Dysregulation of transporters such as ABCC1, ABCB1, and ABCA2 has been linked to neuropsychiatric disorders, yet their expression patterns in schizophrenia and their modulation by antipsychotic treatment remain unclear." (PMID 41465144, 2025). "An RNA sequencing analysis of the PFC suggested a dysregulation of numerous schizophrenia related genes including Olig1, Fgfr1, Gpr17, Gna12, Abca2, Sox1, Dpm2, and Rab2a in the rat model of psychosis." (PMID 39825014, 2025). "The present study aims to address this gap by examining the longitudinal expression patterns of ABCC1, ABCB1, and ABCA2 in individuals with schizophrenia before and after antipsychotic treatment, and by comparing these patterns with those of healthy controls." (PMID 41465144, 2025). "The data suggest that ABCA2 is markedly upregulated by treatment in schizophrenia, which may indicate gene-specific pharmacological activation or a compensatory regulatory mechanism." (PMID 41465144, 2025). "Collectively, these findings underscore the potential gene-specific heterogeneity of ABC transporter biology in schizophrenia: ABCC1 may relate to inflammatory variability, ABCB1 may reflect pharmacodynamic differences, and ABCA2 may index treatment-associated metabolic adaptations." (PMID 41465144, 2025). "By searching for references in PubMed we discovered that 9 of these genes (~ 15% of the total) are already candidates for involvement in diseases including Alzheimers (ABCA2), osteoporosis (COL4A1 and COL4A2) and schizophrenia (SLIT3)." (PMID 15766383, 2005).
neuroblastoma (3 papers, 2015 to 2022). Neuroblastoma (NB) is the most common solid, extracranial childhood tumor. "The mouse ABCA2 (an ortholog of the human ABCA2) has a possible role in regulating cholesterol homeostasis and low-density lipoprotein receptor metabolism in N2 neuroblastoma cells, with knock-out causing a ‘shaky’ (tremor) phenotype." (PMID 26583651, 2015). "In addition, it has been shown that overexpression of ABCA2 in neuroblastoma cells results in decreased cellular cholesterol levels." (PMID 29662553, 2018). "Confocal microscopy identified colocalization of ABCA2 with both Aβ and APP in intracellular vesicles in human neuroblastoma cells." (PMID 35477481, 2022). "However, later research found a decrease in total and membrane cholesterol levels as well as a reduced cholesterol efflux to ApoE ε3 acceptors in mouse neuroblastoma cells expressing human ABCA2, without perturbing lipid rafts." (PMID 35477481, 2022).
breast carcinoma (2 papers, 2014 to 2025). "In contrast, breast cancer exhibited relatively lower deep deletion rates, restricted to ABCG2, ABCC4, ABCA2, ABCC2, and ABCC9." (PMID 40641097, 2025).
colon cancer (2 papers, 2019 to 2023). "ABCB1 and ABCA2 display inverse regulation upon the differentiation of colon tumors." (PMID 31417399, 2019).
leukemia (2 papers, 2016 to 2021). A malignant (clonal) hematologic disorder, involving hematopoietic stem cells and characterized by the presence of primitive or atypical myeloid or lymphoid cells in the bone marrow and the blood. "ABCA2 is a member of ATP-binding cassette (ABC) transporters that transports many kinds of small molecules through membranes and is involved in drug resistance in leukemia cell lines." (PMID 27822437, 2016).
ovarian carcinoma (2 papers, 2004 to 2019). A malignant neoplasm originating from the surface ovarian epithelium. "Gain of 9q34, including the ABCA2 transporter gene and overexpression of ABCA2 mRNA in an ovarian carcinoma cell line has been associated with enhanced efflux of estramustine." (PMID 15150577, 2004).
Sepsis (2 papers, 2023 to 2024). Sepsis is defined as life-threatening organ dysfunction caused by a dysregulated host response to infection. "At the genetic level, seven susceptibility genes for sepsis in severe burn patients were found: DNAH11, LAMA2, ABCA2, ZFAND4, CEP290, MUC20 and ENTPD1." (PMID 36659877, 2023). "Through genomic analysis, we identified seven important susceptibility genes (DNAH11, LAMA2, ABCA2, ZFAND4, CEP290, MUC20 and ENTPD1) in patients with severe burn injuries complicated with sepsis." (PMID 36659877, 2023).
acute myeloid leukemia (1 paper, 2014). Acute myeloid leukemia (AML) is a group of neoplasms arising from precursor cells committed to the myeloid cell-line differentiation. "ABCA2 protein is related to diseases such as, early atherosclerosis, Tangier's, small cell lung cancer, acute myeloid leukemia and Alzheimer's disease early infection." (PMID 25254091, 2014).
anaplastic astrocytoma (1 paper, 2022). "The relative expression level of ABCA2 mRNA was found to be significantly higher in oligodendrogliomas compared to anaplastic astrocytomas or GBM." (PMID 35053843, 2022).
asthma (1 paper, 2009). "The genes involved in the classification were: MGP, Abca2, and Sult1a1, which demonstrated that the transportation and production of steroid hormone may be regulated by acupuncture in the EAR phase of asthma at the level of transcription." (PMID 19419550, 2009). "In our study, Abca2 was up-regulated in asthma, which may correlate with the cell survival in the EAR phase of asthma." (PMID 19419550, 2009).
colitis (1 paper, 2023). Inflammation of the colon. "We observed several upregulated genes associated with colitis and IBD development, including ABCA2, Acss1, Araf, CSAD, Ilf3, and TRAFD1, showing similar fold change patterns across treatment groups." (PMID 37909786, 2023).
glioma (1 paper, 2008). A benign or malignant brain and spinal cord tumor that arises from glial cells (astrocytes, oligodendrocytes, ependymal cells). "Interestingly, ABCA2 and ABCB1 (MDR-1/p-glycoprotein 1) were also more abundantly expressed by TdEC, reflecting the previously reported higher expression of p-glycoprotein 1 in EC from glioma than from normal brain." (PMID 18447899, 2008).
liver cirrhosis (1 paper, 2019). "On the other hand, mutations in ITSN2 were found in tumors without vascular invasion, while mutations of ABCA2 gene were only identified in the tumors of patients without liver cirrhosis." (PMID 31429776, 2019).
mastocytosis (1 paper, 2020). A clonal myeloproliferative neoplasm characterized by the proliferation and accumulation of neoplastic mast cells in one or multiple organs or organ systems. "Four SNPs were more prevalent (in ABCA2, OTX2-AS1, HLA-V, and PDE4DIP genes) and 5 were less prevalent (in RPTN, CYP2B6, OR51Q1, FTCD, and rs9828758 near RP11 genes) in mastocytosis patients compared to a control cohort." (PMID 32752121, 2020).
myeloid leukemia (1 paper, 2012). A clonal proliferation of myeloid cells and their precursors in the bone marrow, peripheral blood, and spleen. "Additionally, detection of ABCA2, ABCB2 and ABCC10, which were found overexpressed in childhood AML, may be worthy to build the gene regulation network in proliferation of myeloid leukemia cells." (PMID 23067006, 2012).
osteosarcoma (1 paper, 2024). A usually aggressive malignant bone-forming mesenchymal neoplasm, predominantly affecting adolescents and young adults. "Given the substantial weight of ABCA2 in the risk assessment, further investigations were conducted to explore its role in mediating drug sensitivity in osteosarcoma." (PMID 38983852, 2024). "We assessed the impact of the Cuproptosis-SPG gene ABCA2 on apoptosis in osteosarcoma cells using flow cytometry." (PMID 38983852, 2024). "Our study found that knockdown of the cuproptosis-SPG gene ABCA2 significantly inhibited the migration ability of osteosarcoma cells, suggesting that the sphingolipid-cuproptosis metabolic network jointly influences the formation of focal adhesions, thereby regulating cancer cell migration." (PMID 38983852, 2024).
rhabdomyosarcoma (1 paper, 2023). A rare aggressive malignant mesenchymal neoplasm arising from skeletal muscle. "One of the articles reported no results using the cellular line of rhabdomyosarcoma, and the other found overexpression of ALDHA3, ALDHB1, ALDHL2, SOX2, ABCG2, ABCB1, and ABCA2 markers." (PMID 37173919, 2023).
sarcoma (1 paper, 2012). A usually aggressive malignant neoplasm of the soft tissue or bone. "Interestingly the ALDH1high population of all sarcoma cell lines demonstrated, with statistic significance, increased expression levels of ABCG2 compared to control or ALDH1low cells, whereas the p value for ABCA2 was not significant." (PMID 22928012, 2012).
temporal lobe epilepsy (1 paper, 2021). A localization-related (focal) form of epilepsy characterized by recurrent seizures that arise from foci within the temporal lobe, most commonly from its mesial aspect. "Similar to this study, increased expression of MOG, PLP1, ABCA2, FA2H, TF, ASPA was demonstrated in high-spiking regions of cortical areas of temporal lobe epilepsy patients." (PMID 34301297, 2021).
cancer (18 papers, 2004 to 2025). A tumor composed of atypical neoplastic, often pleomorphic cells that invade other tissues. "ABCA2 plays a role in regulating cholesterol homeostasis in the brain, facilitating lipid transport, and impacting drug resistance in cancer cells, notably tumor stem cells." (PMID 39238930, 2024). "For instance, we identified phase shifted transcript pairs from different cancer hallmark genes such as BIRC5 in HCT116_WT, PCGF2 in HCT116_ARNTLKO, ABCA2 in HCT116_NR1D1KO, and CHD8 in HCT116_PER2KO." (PMID 35552415, 2022). "Other studies have shown that some ABC transporters, including ABCA2, ABCA3, ABCB1, and ABCG2, are associated with cancer cell stemness." (PMID 34244494, 2021). "In the present study, we performed rare mutation analyses for 12 ABC transporters related to drug resistance (ABCA2, -A3, -B1, -B2, -B5, -C1, -C2, -C3, -C4, -C5, -C6, -G2) in a dataset consisting of RNA sequencing data from 18 cancer patients." (PMID 31991926, 2020). "In the present study, we performed rare mutation analyses for 12 ABC transporters related to drug resistance (ABCA2, -A3, -B1, -B2, -B5, -C1, -C2, -C3, -C4, -C5, -C6, -G2) in a dataset of 18 cancer patients." (PMID 31991926, 2020). "Notably, within a pan-cancer analysis, ABCA2 exhibited a significantly elevated expression in CHOL compared to normal tissues." (PMID 38983852, 2024). "The analysis performed with the U Mann–Whitney test showed that the average expression level of the ABCA2 (p = 0.01) and ABCB1 (p = 0.001) genes was statistically significantly higher in patients associated with the lymphatic vessel infiltration of cancer cells." (PMID 36674773, 2023). "We showed that TFEB expression was increased in PCa tissues, and played a role in the progression of PCa by influencing ABCA2 activity in cancer-related lysosome biogenesis, which might contribute to patient’s poor clinical prognosis." (PMID 33732651, 2021). "In addition, we found some hypermethylated genes with an associated decrease in expression, such as ANK3, TSPYL5, RAB3A and ABCA2 that have been reported to be related with cancer or central nervous system diseases." (PMID 29221210, 2017). "Additionally, PNSTs in the present study showed the highest number of upregulated genes involved in transport mechanisms, including ABCA2, a member of the ABC family of membrane transport proteins previously associated with multidrug resistance in some cancers." (PMID 36099287, 2022). "In addition, silencing ABCA2 expression reduced cancer cell migration ability in PCa (p<0.001)." (PMID 33732651, 2021). "ABCA2 has been suggested to play a role in the transport of steroids, lipids and related molecules and is expressed at high level in brain and neural tissue (The cancer genome anatomy project (2001): Sage Genie, Sage Anatomic Viewer, Digital Northern for ABCA2." (PMID 15150577, 2004). "We further performed Q-RT-PCR to determine the mRNA expression levels of ABCA2, ABCC1, ABCC4, ABCD3, and ABCF2, which are the ABC transporters expressed in all of the skin samples in our semi-quantitative RT-PCR, in normal and cancer skin." (PMID 25505559, 2013). "The expression levels of ABCA2, ABCC4, ABCD3, and ABCF2 in human skin were similar between normal and cancer individuals." (PMID 25505559, 2013). "The ABCA2/8/9 genes belong to the broad ATP-binding cassette (ABC) transporter superfamily, the members of which pump drug molecules out of the cell, thereby decreasing the net accumulation of drugs within cancer cells." (PMID 37444135, 2023).
tumor (11 papers, 2004 to 2025). "Proteins of interest identified by tandem MS-MS that were decreased in sera from tumor-bearing rats that were either OKN-007-treated or untreated included ABCA2, ATP5B, CNTN2, ITGA3, KMT2D, MYCBP2, NOTCH3, and VCAN." (PMID 35053843, 2022). "Silencing of ABCA2 reduced lysosomal biogenesis and decreased matrix metalloproteinases expression, which reduced PCa cell invasion and migration in the tumor microenvironment." (PMID 33732651, 2021). "ABCA2 expression has been observed in tumour cell lines of different origin and intracellular localisation to the endosome/lysosome compartment was demonstrated." (PMID 15150577, 2004). "Moreover, genes such as B4GALNT5 and ABCA2 also showed higher expression patterns, which may be closely related to intracellular material transport and metabolic processes, processes that are crucial for maintaining the tumor-supportive microenvironment." (PMID 41445741, 2025). "From this study, proteins of interest identified by tandem MS-MS that were decreased in sera from tumor-bearing rats treated with OKN-007, compared to untreated, included ABCA2, ATP5B, CNTN2, ITGA3, KMT2D, MYCBP2, NOTCH3, and VCAN." (PMID 35053843, 2022). "In the TFEB knockdown xenograft tumor groups, ABCA2 protein expression was decreased, while an increased expression was observed in TFEB-overexpressing xenograft tumor groups compared to vector groups." (PMID 33732651, 2021). "The average expression level of the ABCA2 (p = 0.000), ABCB1 (p = 0.000), and ABCG2 (p = 0.001) genes was statistically significantly higher in patients with diagnosed tumor cell infiltration into fat tissue compared to patients without tumor cells in the fat tissue." (PMID 36674773, 2023). "The results demonstrate a significant negative correlation between ABCA2 and the infiltration of CD8 T cells, suggesting that ABCA2 may be a critical Cuproptosis-SPG gene influencing anti-tumor immunity." (PMID 38983852, 2024).
ABCA2 also shares sentences with these, for which no sentence is quoted: lung carcinoma (2 papers); atherosclerosis (1); brain tumors (1); central nervous system diseases (1); chronic myeloid leukemia (1); Crohn disease (1); epilepsy (1); frontotemporal dementia (1); infection (1); Insulin resistance (1); intestinal cancer (1); oligodendroglioma (1); osteoporosis (1); prostate tumour (1); psychosis (1); small cell lung carcinoma (1); T-cell acute lymphoblastic leukemia (1).